HIF1A (hypoxia inducible factor 1 subunit alpha)
Diseases named in the same sentence as HIF1A in open-access papers (continued):
Sharing a sentence is not in itself a finding about the gene and the disease.
renal cell carcinoma (191 papers, 2005 to 2025). "For example, mutations in the VHL gene, which destabilize HIF-1α, are common in renal cell carcinoma and drive hypoxia-associated phenotypes." (PMID 39981236, 2025). "We tested this in RCC4 cells, a renal cell carcinoma cell line carrying an inactivating VHL mutation that causes tonic HIF-1α stabilization even under normoxia." (PMID 40552983, 2025). "The increased expressions of HIF1α and HIF2α were associated with an unfavorable prognosis in patients with renal cell carcinoma." (PMID 39064555, 2024). "The hypoxia-inducible factor 1α (Hif1α) is frequently upregulated in renal cell carcinoma, usually following a loss of function of the Von Hippel–Lindau tumor suppressor (VHL)." (PMID 39518998, 2024). "TRIB3 has been associated with HIF-1α in renal cell carcinoma patients with HIF-1α binding to multiple regions in the TRIB3 promoter resulting in upregulation of TRIB3 expression." (PMID 38896446, 2024). "Similar to our observation, renal cell carcinoma patients with variant HIF1A alleles including A588T were shown to present in low tumour stages." (PMID 34708297, 2022). "Alterations in metabolic pathways caused by HIF1A are important for the initiation and progression of renal cell carcinoma." (PMID 36552042, 2022). "Our data suggesting that SphK1/S1P signaling activation is associated with HIF-1α expression in osteosarcoma are in line with our previous findings in prostate and renal cell carcinoma cell models." (PMID 35158767, 2022). "HIF1α and HIF2α have been shown to have opposite effects on renal cell carcinoma (RCC) xenograft tumor growth, which were associated with their antagonistic effects towards the c-Myc oncogenic activity." (PMID 32545251, 2020). "For example, Von Hippel-Lindau factor (VHL) deletion and inactivation are among the most common mutations observed in renal cell carcinoma leading to oncogenic stabilization of HIF-1α." (PMID 28548087, 2017). "HIF-1α is often highly active in renal cell carcinoma due to mutations in VHL and subsequently accumulation of HIF-1α." (PMID 27906674, 2017). "A recent genome-wide association study identified mutations affecting the UPS pathway in renal cell carcinoma, which were associated with increased levels of HIF-1α in these tumors." (PMID 23800266, 2013). "Our laboratory had previously demonstrated that the combination of rapamycin and panobinostat resulted in HIF-1α protein degradation associated with a reduction in tumor angiogenesis of prostate and renal cell carcinoma xenograft models." (PMID 22087262, 2011). "The hypericin effect also eliminates the high HIF-1α levels expressed constitutively in the von-Hippel Lindau protein (pVHL)-deficient RCC-C2VHL−/− renal cell carcinoma cell line." (PMID 21949677, 2011). "Moreover, it has been reported that the expression of PD-L1 is associated with GLUT1 and HIF-1α expressions in patients with pulmonary pleomorphic carcinoma and renal cell carcinoma (RCC)." (PMID 33441183, 2021). "The vital role of HIF transcription factors is reflected by the fact that their mutations are very rare in cancers: at low frequency, HIF1α mutation can be detected in renal cell cancer, while HIF2α mutation results in the development of a rare tumor, paraganglioma." (PMID 34257622, 2021). "Biallelic VHL inactivation in renal cell carcinoma (RCC) is indeed associated with increased HIF-1α, which is responsible for the highly vascular nature of RCC." (PMID 33467713, 2021). "MTHFD2 has been reported to affect the protein modulation of HIF1α by regulating m6A modification in renal cell carcinoma, which leads to decreased glycolytic capacity of renal tumor cells." (PMID 40280919, 2025). "Recent studies have shown that DEPDC1 regulates glycolysis in renal cell carcinoma through the AKT/mTOR/HIF1α pathway." (PMID 40722708, 2025). "Of note, expression of TLS-polymerases correlates with VEGFA (primary HIF1α target) in a database of renal cell carcinoma, a cancer which accumulates HIF1α." (PMID 39468223, 2025).
renal cell carcinoma (continued). "Initially, we investigated the protein expression of BNIP3 and HIF-1α in renal cell carcinoma cell lines A498, 786-O, CAKI-1, ACHN, and GRC." (PMID 40837014, 2025). "In VHL-deficient renal cell carcinoma (RCC), HIF-2α has been demonstrated to be the key oncogenic driver, while HIF-1α also contributes by supporting tumor metabolism." (PMID 40427061, 2025). "In renal cell carcinoma, the lncRNA H19 acts as a molecular sponge for miR-29a, derepressing HIF-1α expression and fostering tumor growth." (PMID 38279330, 2024). "Another SNP, rs67311347, enhances the expression of ENTPD3-AS1, which acts protectively in renal cell carcinoma (RCC) by inhibiting cell proliferation via the miR-155–5p/HIF-1α pathway." (PMID 38249783, 2024). "Their study also reported that the Snp-mediated upregulation of lncRNA-ENTPD3-AS1 suppressed renal cell carcinoma (RCC) via the mir-155/HIF1A pathway." (PMID 38368317, 2024). "P300 is a transcriptional component of HIF1α, which acetylates HIF1α at Lys-709, increasing its stability as shown in both osteosarcoma and renal cell carcinoma cell lines." (PMID 38279330, 2024). "High MIF and DDT expression in the kidney impacts renal cell carcinoma (RCC) progression through interactions with HIF1α and HIF2α." (PMID 38732068, 2024). "SART1 is a spliceosome protein that mediates the degradation of the HIF1-α protein and facilitates the proliferation of renal cell carcinoma (RCC) cells." (PMID 39004717, 2024). "The two main HIFα isoforms, HIF1α and HIF2α, have opposing effects on renal cell carcinoma biology, with HIF1α acting as a tumor suppressor, whereas HIF2α is an oncogene." (PMID 36728187, 2023). "It is reported that liprin-α4 is up-regulated under hypoxic conditions and is directly regulated by HIF-1α in renal cell carcinoma." (PMID 35382861, 2022). "Collectively, these data suggesting that SphK1/S1P signaling is required for the regulation of HIF-1α in osteosarcoma are in line with our previous findings in prostate and renal cell carcinoma cell models." (PMID 35158767, 2022). "STAT3 is a transcription factor that enhances the progression of urothelial cells from carcinoma in situ to invasive bladder cancer and regulates the angiogenesis of RCC (renal cell carcinoma) through upregulating HIF1α and VEGF expression." (PMID 35123491, 2022). "The results of studies have demonstrated that renal cell cancers expressing solely HIF-2α displayed enhanced proliferation in rats compared to those with a co-expression of HIF-1α and HIF-2α." (PMID 35328822, 2022). "The upregulation of LncRNA ENTPD3-AS1 inhibits cell proliferation and migration through the miR-155-5p/HIF-1α pathway in renal cell carcinoma." (PMID 34218253, 2021). "HSP70 is also involved in angiogenesis by binding and stabilizing hypoxia inducible factor-1 alpha (HIF-1α) in renal cell carcinoma." (PMID 33808130, 2021). "Hypoxia-inducible factor 1α (HIF-1α) is an important regulator of cancer metabolism, angiogenesis and migration which is produced in renal cell carcinoma (RCC)." (PMID 34239445, 2021). "With regards to renal cell carcinoma (RCC), past researchers have identified that the hypoxia inducing factors 1α (HIF-1α) and its linked pathways such as ubiquitin–proteasome and rapamycin pathways are major contributors in RCC tumorigenesis." (PMID 33468235, 2021). "Our findings reveal that SNP-mediated lncRNA-ENTPD3-AS1 upregulation suppresses renal cell carcinoma via miR-155/HIF-1α signaling." (PMID 34218253, 2021). "Using such a combined approach in metastatic renal cell cancer, it was possible to demonstrate that high HIF1α and low HIF2α expressions or a “HIF-index” are poor prognostic factors, when CAIX, GLUT1 and GAPDH overexpressions follow this prognostic trend." (PMID 34257622, 2021).
renal cell carcinoma (continued). "To study the distinct transcriptional responses provoked by HIF1α or HIF2α in renal cell carcinoma (RCC), we used WT8 cells that were generated by restoration of VHL expression into the 786-O VHL deficient RCC cell line." (PMID 33321829, 2020). "HIF‐2α induction, by contrast, has been shown to counteract HIF‐1α‐dependent cell cycle arrest in renal cell carcinoma lines, thereby resulting in enhanced proliferation dependent on c‐Myc gain‐of‐function." (PMID 32686360, 2020). "For instance, SNHG12 upregulation increased the expression of hypoxia-inducible factor 1 α (HIF1α) by targeting miR-199a-5p, which induced cell proliferation, migration, and invasion in renal cell carcinoma." (PMID 33124951, 2020). "In view of our findings, we have come to the conclusion that QKI inhibits the development of renal cell carcinoma by decreasing the expression of HIF-1α." (PMID 32047543, 2020). "Here we have extended the analysis to some other HIF1α and HIF2α-dependent genes in an in vitro cell model of human renal cell carcinoma as well as in mice with Vhl gene inactivation in which HIF1α and HIF2α isoforms are constitutively activated." (PMID 33321829, 2020). "TGase 2 is negatively regulated by von Hippel-Lindau tumor suppressor protein (pVHL) and positively regulated by hypoxia-inducible factor 1-α (HIF-1α) in renal cell carcinoma (RCC)." (PMID 32260198, 2020). "Recently, Carbonic anhydrase 9, a validated HIF-1α target, was identified in renal cell carcinoma cell-derived exosomes and was increased upon hypoxia treatment, which promoted migration and tube formation of human umbilical vein endothelial cells (HUVECs)." (PMID 30925935, 2019). "From renal cell carcinoma (RCC), it is known that chromosome 3 loss leads to VHL inactivation, and a subsequent increase in HIF1a." (PMID 31323773, 2019). "Other groups reported that HIF‐1α expression was positively correlated with the expression of CD133 in renal cell carcinoma (RCC) tissues and with the ALDH1 expression in astrocytoma." (PMID 30536571, 2019). "Since miR-126 was found to inhibit HIF-1α protein expression and miR-126 deactivation induced a pseudohypoxia in renal cell carcinoma model, it indicates a potential correlation between hypoxia and miR-126+ MDSC-Exo-mediated immunosuppression." (PMID 30925935, 2019). "Other EMT regulators, such as Zeb1, Zeb2, and TCF-3, have been reported to be upregulated in pVHL-null renal cell carcinoma in which HIF-1α is constitutively overexpressed." (PMID 30696468, 2019). "The most related pathway to SOX2OT inhibition was renal cell carcinoma (Kegg: 05211, corrected p value = 0.004953) with 5 genes differentially expressed in RNA sequences of both cells (hif1a, hras, pik3ca, rap1b, vhl)." (PMID 30202240, 2018). "HIF1α is also known to be important in the progression of several cancers, including renal cell carcinoma; therefore, HIF1α expression was assessed." (PMID 27230676, 2016). "A study by Bianchi C indicated that ANXA3 is participated in Renal cell carcinoma metastasis through stimulating angiogenesis by increased VEGF level promoted by HIF-1a." (PMID 27894078, 2016). "Taken together, these data suggest that PIG3 was involved in HIF-1α regulation, and reveal a novel signaling pathway of PIG3/HIF-1α in the regulation of cell migration in renal cell carcinoma." (PMID 27029070, 2016). "Type 2 VHL disease shows a high risk of pheochromocytoma (PCC) and germ line missense mutations is subdivided into high risk (2B), low risk (2A), or absence (2C) of Renal cell carcinoma (RCC) and heamangioblastoma is correlated with function of pVHL to impair HIF-1α activity." (PMID 26503325, 2015). "Recently, a similar finding demonstrated that Se-methylselenocysteine inhibited HIF-1α in renal cell carcinoma through a PHD2-dependent and Von-Hippel-Lindau-independent degradation mechanism." (PMID 24515947, 2014).
renal cell carcinoma (continued). "In hypoxic tumor cells, reactive oxygen species increase HIF-1α transcription via the PI3K/Akt pathway, and silencing of HIF-1α suppresses tumorigenicity of renal cell carcinoma through the regulation of the PI3K/Akt pathway." (PMID 24765145, 2014). "Research reported that HIF-1α was up-regulated in chronically SDHB-silenced Hep3B cells, HIF-1α was overexpressed in SDH-deficient leiomyomas and renal cell cancer (HLRCC)." (PMID 25491408, 2014). "From other tumours, in particular renal cell cancer, we know that hypoxia-inducible factor 1, alpha subunit (HIF1A) signalling mediates expression of VEGF, platelet-derived growth factor (PDGF) and angiopoietin via the PI3K/mTOR pathway." (PMID 24398114, 2014). "Hypermethylation of the VHL promoter in renal cell carcinoma has been correlated with increased HIF1a expression, and deletion of miR-23b has been reported to reduce HIF1a and VEGFA expression via its targeting of VHL." (PMID 23560444, 2013). "MUC1, an O-glycoprotein membrane-bound mucin, is a HIF-1α target that plays a role in regulating the migration and invasive property of renal cell carcinoma cells." (PMID 23241400, 2012). "CXCR4 was found to be transactivated by hypoxia-induced factor-1α (HIF-1α) at the transcriptional level in renal cell carcinoma." (PMID 23082154, 2012). "The resulting high constitutive HIF-1α intracellular accumulation generates highly vascularized tumors as renal cell carcinoma or hemangioblastoma." (PMID 21949677, 2011). "For example, von Hippel-Lindau is a tumor suppressor protein that contributes to the transformation of certain types of cancer, such as renal cell carcinoma, via negative regulation of HIF-1α." (PMID 21320311, 2011). "Renal cell carcinoma also exhibits some sensitivity to mtor inhibitors, likely because of the importance of mtor signalling in the expression of Hif1A (hypoxia inducible factor 1, alpha subunit), a key player in angiogenesis and the growth of renal tumours." (PMID 19229373, 2009). "This study aims to elucidate whether L-2-HG regulates the function of HIF1A through histone lactylation modification, thereby contributing to brain metastasis in renal cell carcinoma (RCC)." (PMID 41198650, 2025). "Notably, ST expression and concentration are raised in renal cell carcinoma, and this has been mechanistically connected to ST upregulation by HIF1α." (PMID 38943216, 2024). "The downregulation of HIF-1α target genes by mTORi prevented the growth of renal cell carcinoma." (PMID 36745547, 2023). "It is possible that these tumors may behave similar to renal cell carcinoma (RCC) in which HIF-2α GoF and HIF-1α loss-of-function (LoF) occur during cancer progression." (PMID 36480544, 2022). "In addition, we find that YAP1 nuclear localization is markedly elevated in renal cell carcinoma (RCC), along with its association with HIF1α; this is significant, because VHL is often mutated and is a well-known tumor suppressor in RCC." (PMID 35937460, 2022). "Finally, immunohistochemical analyses in patient biopsies with renal cell carcinoma showed that elevated HIF-1α correlates with increased ALS2 expression." (PMID 33339852, 2020). "We next asked if this trend could also be observed in renal cell carcinoma, a malignancy which frequently harbors VHL mutations leading to constitutive activation of HIF-1α." (PMID 31819034, 2019). "Furthermore, quite recently it was demonstrated that HIF1α represses PGC1α expression in renal cell carcinoma, suggesting a regulatory loop among these transcriptional factors, involving oxygen sensing to mitochondrial biogenesis." (PMID 30466459, 2018). "Nonetheless, inhibition of constitutive HIF-1α expression in renal cell carcinoma cell lines, mouse embryonic fibroblasts (MEF), 293 cells, and significant reduction of constitutive VEGF-A production in a retinal pigmental epithelial cell line has been described." (PMID 28445935, 2017).
renal cell carcinoma (continued). "In addition, STAT3 promotes the progression from carcinoma in situ to invasive bladder cancer and modulates renal cell carcinoma angiogenesis by increasing the expression of HIF1α and VEGF." (PMID 28031890, 2015). "HIF-1α has previously been shown to play an important role in renal cell carcinoma." (PMID 25373733, 2014). "Clear-cell renal cell carcinoma (RCC) is, in most cases, caused by loss of function of the tumor suppressor gene von Hippel–Lindau, resulting in constitutive activation of hypoxia-inducible factor (HIF)-1α and expression of hypoxia-induced genes in normoxic conditions." (PMID 23185271, 2012). "To determine whether the sirtinol-induced repression of HIF-1α protein is dependent on VHL, we used a VHL-deficient renal cell carcinoma, RCC4 VHL−/− and a VHL reconstituted, RCC4 VHL+/+ cell lines." (PMID 22479397, 2012). "Nevertheless, we showed that the plasma CAIX detected in patients with NSCLC is much lower than CAIX concentrations described in renal cell carcinoma, because the very high constitutive HIF-1α levels in these latter tumours and also differences in CAIX expression depending on the cell type." (PMID 20461082, 2010). "Interestingly, there is evidence that tumorigenesis of renal cell carcinoma is associated with overexpression of HIF-2α, while HIF-1α inhibits tumor growth." (PMID 20224786, 2010). "Recent studies showed that HIF-1α antagonizes c-Myc function and inhibits VHL-deficient renal cell carcinoma (RCC) growth, while HIF-2α enhances c-Myc activity in WT-8 and 786-O cells that predominantly express HIF-2α (but little HIF-1α) and promotes VHL-deficient RCC tumorigenesis." (PMID 20046830, 2009). "In the microenvironment of renal cell carcinoma (RCC), TAMs transcriptionally upregulate miR-193a-5p via HIF-1α." (PMID 41019994, 2025). "For example, genetic mutations of von Hippel-Lindau (VHL) in renal cell carcinoma (RCC) lead to exceptionally high expression of VEGF through stabilization of hypoxia-inducible factor (HIF)-1α that transcriptionally controls VEGF mRNA expression." (PMID 38482486, 2024). "Renal cell carcinoma (RCC) are characterized by frequent VHL (Von Hippel-Lindau) mutations—which, by activating the pathways related to HIF-1α and further VEGF (Vascular Endothelial Growth Factor), makes them highly angiogenic tumors." (PMID 35625614, 2022). "In clear cell renal cell carcinoma (ccRCC), the most common histological variant of RCC, the Von Hippel-Lindau (VHL) tumor suppressor gene is silenced, which leads to activation of hypoxia inducible transcription factors, HIF-1α and HIF-2α." (PMID 34731180, 2021). "We first investigated whether PIG3 regulated HIF-1α expression in human renal cell carcinoma cell." (PMID 27029070, 2016). "Benzonana and co-workers exposed renal cell carcinoma cells (RCC4) to 0.5-2% isoflurane and found that HIF-1α production was dose-dependently induced and HIF-1α expression was induced through the PI3K/Akt pathway." (PMID 40881864, 2025). "In renal cell carcinoma, TRIM21 targets HIF-1α for ubiquitin-mediated degradation, thereby suppressing HIF-1α-dependent glycolytic programming in tumor cells." (PMID 40735642, 2025). "HIF-1α binds to the putative HIF-responsive element present in the Nr4a1 promoter, thereby including NR4A1 expression in renal cell carcinoma." (PMID 38539632, 2024). "Conversely, PHD inhibitors that inhibit and stabilize HIF-1α degradation have been employed as pharmacological agents for renal anemia, while HIF-2α inhibitors have been utilized in the treatment of renal cell carcinoma." (PMID 39273346, 2024). "The next step is to explore how DEPDC1 regulates the AKT/mTOR/HIF1α pathway and key glycolytic enzymes, and to verify the effects of DEPDC1 in primary drug-resistant tumor animal models of renal cell carcinoma." (PMID 39068164, 2024).